TRPM8 (transient receptor potential cation channel subfamily M member 8)
Diseases named in the same sentence as TRPM8 in open-access papers (continued):
Sharing a sentence is not in itself a finding about the gene and the disease.
peripheral neuropathy (10 papers, 2012 to 2025). A disorder affecting the peripheral nervous system. "The cool sensor transient receptor potential melastatin channel 8 (TRPM8) is highly expressed in trigeminal and dorsal root ganglia, playing a key role in cold hypersensitivity associated to different peripheral neuropathies." (PMID 32843690, 2020). "Recent studies demonstrate that TRPM8 can promote local vasodilation which can aggravate platinum-induced peripheral neuropathy." (PMID 35361751, 2022). "In primary sensory neurons, the overexpression of TRPM8 mRNA and protein in oxaliplatin-induced peripheral neuropathy seems also to be mediated through the c-Myc regulatory gene." (PMID 35269831, 2022). "Thus, α‐acyloxy carboxamide 23 appears as a promising therapeutic candidate to topically intervene on TRPM8‐mediated peripheral neuropathies." (PMID 40123199, 2025). "L-OHP-induced acute peripheral neuropathy is associated with calcium channels, such as TRPM8 and TRPA1, and sodium channels in the dorsal root ganglion (DRG), whereas chronic peripheral neuropathy is correlated with damage to nerve and ganglion cells by L-OHP accumulation." (PMID 37069612, 2023). "Given the previous findings, AMTB may also plays a role in alleviating platinum-induced peripheral neuropathy through antagonizing TRPM8." (PMID 35361751, 2022). "The high expression of TRPM8 channels both in sensory neurons and organs, in addition to their activation by cold, point to these channels as mediators of cold-induced nociception and cold-hypersensitivity developed in certain peripheral neuropathies." (PMID 35269831, 2022). "The DRG TRPM8 neurons are also involved in oxaliplatin's chronic painful peripheral neuropathy." (PMID 35634452, 2022). "TRPM8 modulation could also serve to alleviate pain suffering in processes that occur after inflammation, nerve injury or peripheral neuropathies." (PMID 34445208, 2021). "Several studies examine the involvement of TRPM8 in oxaliplatin-induced peripheral neuropathy." (PMID 22839205, 2012). "These cold-specific alterations in peripheral neuropathies may be driven by damage of cool-sensitive primary afferents, likely expressing transient receptor potential channel melastin (TRPM8), the lack of which leads to loss of cold sensation in mice." (PMID 35264694, 2022). "In this study, we used a mouse model to investigate whether TRPA1, TRPM8, and TRPV1 are involved in the oxaliplatin-induced acute peripheral neuropathy." (PMID 22839205, 2012). "Lysophosphatidylcholine (LPC) 18:1 and LPC 16:0, which are over-expressed in oxaliplatin-induced peripheral neuropathy, have been identified as endogenous activators of TRPV1 and TRPM8 channels, suggesting that the modulation of lipid pathways could also serve to alleviate this neuropathy." (PMID 34445208, 2021). "Thus, although TRPM8 involvement in oxaliplatin-induced subacute peripheral neuropathy remains to be clarified, our findings seem to rule out an important role for TRPM8 in oxaliplatin-induced acute peripheral neuropathy." (PMID 22839205, 2012).
prostate (6 papers, 2016 to 2022). "In prostate carcinogenesis, androgens are known to control the expression of the transient receptor potential melastatin 8 (TRPM8) protein via activation of androgen receptor (AR)." (PMID 31501416, 2019). "Recently, by combining a multidisciplinary approach to an in vitro genetic platform, we demonstrated that the combination of potent TRPM8 agonists with X-rays induces a massive apoptotic response in radioresistant pre-malignant and malignant models of primary prostate lesions." (PMID 34514058, 2021). "Interestingly, (Transient Receptor Potential Melastatin member 8) TRPM8 calcium permeable channel expression is differentially regulated during prostate carcinogenesis, thereby suggesting a potential functional role for this channel in those cell processes, which are important for PCa evolution." (PMID 27409624, 2016).
adenocarcinoma (3 papers, 2010 to 2023). A common cancer characterized by the presence of malignant glandular cells. "Our results show that in the ER+ adenocarcinomas which over-expressed TRPM8, 42.8% (6/14) were grade I, 42.8% (6/14) were grade II and 14.2% (2/14) were grade III." (PMID 20482834, 2010).
infection (3 papers, 2020 to 2024). The state of being infected such as from the introduction of a foreign agent such as serum, vaccine, antigenic substance or organism. "Thus, TRPM8 activation by either cold or menthol appears to drastically attenuate infection, and this may be a product of TRPV1 antagonism." (PMID 32231022, 2020). "Inducing “cold” by stimulating transient receptor potential cation channel subfamily M member 8 (TRPM8) with menthol led to reduced infection and also resulted in lower levels of mitochondrial fission during infection." (PMID 32231022, 2020). "TRPM8 has been shown to antagonize TRPV1, and thus we hypothesize that stimulating TRPM8 blocks TRPV1-mediated mitochondrial fragmentation following CVB exposure and attenuates infection." (PMID 32231022, 2020). "Notably, TRPM8 silencing reversed these effects, suggesting that the activation of TRPM8 suppresses mitochondrial fission proteins, like dynamin-related protein 1 (DRP1), to counteract TRPV1-induced mitochondrial fission, ultimately leading to a decrease in infection and inflammation." (PMID 39062591, 2024).
metabolic disorders (2 papers, 2017 to 2022). "Deficiency of TRPM8 induces numerous metabolic disorders, indicating an alteration of lipid metabolism." (PMID 35682765, 2022). "On the other hand, the size of the therapeutic window of menthol in metabolic diseases may depend on the expression of TRPM8 in those tissues." (PMID 29088850, 2017).
nervous system disease (2 papers, 2022 to 2023). "It appears that TRPM8 plays a complex role in neuroprotection and neurological disorders." (PMID 35897101, 2022). "One disease also matches different targets; for example, nervous system disease can involve CYP19A1, TRPM8, CHRM2, etc." (PMID 37701374, 2023).
neurodegenerative disease (2 papers, 2024). A disorder of the central nervous system characterized by gradual and progressive loss of neural tissue and neurologic function. "TRPM8 ion channel has been found to be crucial molecular component in progression of neurodegenerative diseases like Alzheimer's." (PMID 39150496, 2024).
cardiovascular diseases (1 paper, 2024). "While research on TRPM8 has largely focused on tumors, cardiovascular diseases and pain, its role in bone metabolism remains underexplored, particularly its impact on osteoclasts." (PMID 39170742, 2024).
respiratory disorders (1 paper, 2014). "Recent observations of TRPM8 expression in vagal neurons innervating bronchopulmonary tissue have brought up TRPM8 as a drug target for various respiratory disorders." (PMID 25257900, 2014).
TRPM8 also shares sentences with these, for which no sentence is quoted: ulcerative colitis (3 papers); colorectal adenocarcinoma (2); inflammatory bowel disease (2); Insulin resistance (2); skin cancer (2); trigeminal neuralgia (2); abdominal aortic aneurysm (1); allergic rhinitis (1); Allergy (1); Alzheimer disease (1); breast ductal adenocarcinoma (1); Cerebral ischemia (1); chronic pancreatitis (1); chronic rhinosinusitis (1); Cough (1); Crohn disease (1); dementia (1); digestive system disorder (1); dyslipidemia (1); eczema (1); experimental autoimmune encephalomyelitis (1); familial hemiplegic migraine (1); Glucose intolerance (1); head and neck carcinoma (1); headache disorder (1); hematopoietic neoplasm (1); Hepatic steatosis (1); infarction (1); inflammation (1); invasive breast carcinoma (1).
A further 23 diseases each share a sentence with TRPM8 in 1 paper.